KLF11 (KLF transcription factor 11)
Diseases named in the same sentence as KLF11 in open-access papers (continued):
Sharing a sentence is not in itself a finding about the gene and the disease.
pancreatic cancer (8 papers, 2011 to 2025). "In pancreatic cancer cell lines bearing Kras mutation, the interaction between KLF11 and SMAD3 is inhibited, and treatment with ERK pathway inhibitors such as U0126 (highly selective inhibitor of mitogen-activated protein kinase kinase 1/2–MEK1/2) can revert the Kras effect." (PMID 37239940, 2023). "In pancreatic cancer cells harboring oncogenic Ras mutations, the Erk-MAPK pathway phosphorylates KLF11, thereby impairing its association with mSin3A corepressor and inhibiting Smad7 suppression." (PMID 40230862, 2025). "KLF11 is expressed in the normal pancreas; however, in pancreatic cancer cells, its expression is heterogenous." (PMID 37239940, 2023). "For instance, in pancreatic cancer cells, due to the oncogene-RAS mutation, the KLF11-mSin3a interaction that as a vital part of the “strengthen route” is disrupted by the phosphorylation of KLF11." (PMID 37199905, 2023). "KLF11 is involved in the progression of a wide variety of cancers, such as ovarian cancer and pancreatic cancer." (PMID 32331236, 2020). "In vivo, KLF11 partly inhibits the growth of pancreatic tumor cells of KRAS mutant xenografts, by inducing cell cycle arrest at the S phase via downregulation of cyclin A2." (PMID 32331236, 2020). "We also performed tumorigenesis assays in vivo, injecting flanks of athymic nude mice with L3.6 pancreatic cancer cells transfected with EV, KLF11 WT, or KLF11ΔHP1." (PMID 22318730, 2012). "In fact, different studies have isolated different molecules, like KLF11, retinoblastoma, thioredoxin, which are involved in Smad7 dependent aggressiveness of pancreatic cancer." (PMID 22195733, 2011). "However, the role of KLF11 in tumor cell has shown to be reversed in several cancer types, including pancreatic cancer, ovarian cancer, etc.." (PMID 37199905, 2023). "Furthermore, recruitment of HP1α and SUV39H1 by KLF11 suppresses the activation of genes regulated by KLF11, which consequently promotes apoptosis and inhibits pancreatic cancer growth." (PMID 35159030, 2022). "In pancreatic cancer cells with oncogenic Ras mutations, this function of KLF11 is inhibited by the oncogenic Erk/MAPK: Erk/MAPK phosphorylates KLF11, which leads to the disruption of the KLF11–mSin3a interaction." (PMID 32331236, 2020). "The inactivation of KLF11 results in diminished TGF-β signaling, which facilitates the growth of pancreatic cancer." (PMID 40230862, 2025). "Further, KLF11 suppressed expression of the ROS scavenger genes superoxide dismutase 2 (SOD2) and catalase 1 in pancreatic cancers." (PMID 35406507, 2022). "However, in pancreatic cancer, oncogenic KRAS activates the ERK pathway, which, in turn, phosphorylates KLF11, and abrogates KLF11/SIN3a interaction, leading to transcriptional activation of SMAD7 and tumor progression." (PMID 37239940, 2023).
Hyperglycemia (6 papers, 2014 to 2025). An increased concentration of glucose in the blood. "Diabetic mice with overexpression of KLF11 gene in livers significantly ameliorated hyperglycemia and glucose intolerance; in contrast, the knockdown of KLF11 expression in db/m and C57BL/6J mice livers impaired glucose tolerance." (PMID 24586865, 2014). "We showed that adenovirus-mediated overexpression of KLF11 in livers of db/db diabetic mice alleviated hyperglycemia and glucose intolerance." (PMID 24586865, 2014). "Additionally, gain- and loss-of-function experiments were conducted to investigate the role of KLF11 in hyperglycemia-induced endothelial cell dysfunction." (PMID 39462409, 2024).
breast carcinoma (5 papers, 2020 to 2025). "In breast cancer, the KLF11 promotor is also hypermethylated, and the hypermethylation is associated with low expression of KLF11." (PMID 32331236, 2020). "This influence of miR-30d on breast cancer cell growth, metastasis, and EMT is dependent on a low level of KLF11 and on a high level of pSTAT3." (PMID 32331236, 2020).
depression (5 papers, 2012 to 2020). "In mammals, KLF11/TIEG2 and MAO (monoamine oxidase) signaling is increased in the prefrontal cortex by chronic social defeat and is associated with depression and KLF11 regulates the MAO response." (PMID 32748368, 2020). "Additionally, in sample 1, KLF11 methylation was correlated with Beck Depression Inventory (BDI-II) scores." (PMID 32524199, 2020). "Patients with depression and animal models of depression show changes in miRNA expression as well as the levels of transcription factors, such as KLF11 and R1." (PMID 30271325, 2018). "In synopsis with previous findings implicating KLF11 in depression-related phenotypes, this finding is of mechanistic relevance and might foster research efforts into exploring innovative therapeutic approaches targeting this pathway in the treatment of major depression." (PMID 32524199, 2020). "Correspondingly, a negative correlation of KLF11 DNA methylation with dimensional symptoms of depression (as evaluated via the BDI-II) was observed in the PD patient group." (PMID 32524199, 2020). "MDD patients without anxious features showed nominally decreased KLF11 methylation in comparison to MDD patients with anxious depression (p = 0.052)." (PMID 32524199, 2020). "The present results suggest KLF11 promoter hypomethylation as a potential epigenetic marker of MDD comorbidity in PD or of non-anxious depression, respectively, possibly constituting a differential pathomechanism in anxiety and mood disorders." (PMID 32524199, 2020). "Thus, against the theoretical background of a common biological trunk shared by anxiety and mood disorders, KLF11 methylation could be instrumental in guiding the differentiation of the clinical phenotype toward depression- rather than panic-related symptoms." (PMID 32524199, 2020). "In conclusion, the present pilot data suggest KLF11 promoter hypomethylation as a potential epigenetic marker of MDD comorbidity in PD or non-anxious depression, respectively, possibly contributing to a differential pathomechanism of anxiety and mood disorders." (PMID 32524199, 2020). "Furthermore, in an independent sample of MDD patients, MDD patients without anxious features showed nominally significantly decreased KLF11 methylation levels as compared to MDD patients with anxious depression." (PMID 32524199, 2020). "Additionally, since no control group was available for the MDD sample (sample 2), the observed differences of KLF11 methylation in MDD patients with or without anxious depression cannot be clearly ascribed to the effects of anxious symptoms." (PMID 32524199, 2020).
endometriosis (5 papers, 2013 to 2023). The growth of functional endometrial tissue in anatomic sites outside the uterine body. "For example, KLF11 is highly expressed in human urogenital tissues, and aberrant KLF11 expression has been linked to the pathogeneses of common uterine diseases, such as endometriosis and leiomyoma." (PMID 26223982, 2015). "Our studies further showed that selective and specific loss of Klf11, in contrast to Klf9, was associated with the development of a characteristic phenotype that resembled advanced human endometriosis in a murine disease model." (PMID 23555910, 2013). "In summary, we identify a novel pathogenic role for KLF11 in preventing de novo disease-associated fibrosis in endometriosis." (PMID 23555910, 2013). "To confirm that the observed endometriotic phenotype in these knockout animals was specifically due to loss of Klf11-mediated transcriptional regulation, we also induced endometriosis in Klf9-/- animals." (PMID 23555910, 2013). "Loss of Klf11 results in a prominent fibrotic response in association with induction of endometriosis." (PMID 23555910, 2013). "We found that KLF11 expression was diminished in human endometriosis implants and further investigated its pathogenic role in Klf11-/- knockout mice with surgically induced endometriotic lesions." (PMID 23555910, 2013). "The data therefore suggests that KLF11 has a pathogenic role in endometriosis resulting in lesion growth and prolific fibrotic scarring." (PMID 23555910, 2013). "KLF11 KO mice were associated with progressive fibrosis in a murine model of endometriosis." (PMID 35413089, 2022). "This approach has enabled us to use the system effectively not only for objectively evaluating the effect of loss of Klf11 or Klf9 on the pathogenesis of endometriosis, but also to investigate the effect of planned environmental and therapeutic interventions designed to arrest this process." (PMID 23555910, 2013). "Therefore, using a robust, combinatorial in vitro and in vivo approach, we not only identify a novel pathogenic role for KLF11 in endometriosis, but also characterize the phenotypic consequences that arise out of dysregulated transcriptional regulation from aberrant expression of this gene." (PMID 23555910, 2013). "For example, in the current study the Klf11-/- genetic background allowed us to define a novel role for this human disease-related gene in endometriosis in contrast to its paralog Klf9." (PMID 23555910, 2013). "In order to evaluate the specificity of Klf11 in the pathogenesis of endometriosis, we also surgically induced endometriosis in Klf9-/- mice." (PMID 23555910, 2013). "As we found KLF11 to be diminished in endometriosis tissue, we further investigated its role in disease pathogenesis in vivo in Klf11-/- mice." (PMID 23555910, 2013). "KLF11 expression levels in both epithelial and stromal cells were significantly diminished in endometriosis lesions compared to eutopic endometrium (representative samples)." (PMID 23555910, 2013). "In this study we identify and describe for the first time a role for the Sp/KLF family transcription factor KLF11 in endometriosis." (PMID 23555910, 2013). "In this study, we evaluated the role of the Sp/KLF transcription factor KLF11/Klf11 in the pathogenesis of endometriosis." (PMID 23555910, 2013). "In this study we investigated the role of KLF11 in endometriosis, a common, debilitating, endocrine hormone driven female urogenital disorder." (PMID 23555910, 2013). "As KLF11 expression was diminished in endometriotic implants compared to uterine endometrium, to further characterize the specific role of KLF11 in endometriosis in vivo, we investigated its effect on disease pathogenesis in a Klf11-/- knockout mouse model." (PMID 23555910, 2013). "In summary, we have identified here a novel role of the human disease gene KLF11 in endometriosis." (PMID 23555910, 2013).
endometriosis (continued). "In order to determine if KLF11 may have a role in endometriosis, we used immunohistochemistry to evaluate its expression in a TMA consisting of paired eutopic uterine endometrium and ectopic endometriotic implants from 28 patients." (PMID 23555910, 2013).
leiomyoma (5 papers, 2012 to 2023). A well-circumscribed benign smooth muscle neoplasm characterized by the presence of spindle cells with cigar-shaped nuclei, interlacing fascicles, and a whorled pattern. "Loss of KLF11 expression is associated with increased PGR signaling and proliferation of leiomyoma cells." (PMID 35884847, 2022). "KLF11 protein levels in all 6 subjects were significantly lower (30%) in leiomyoma compared with myometrial tissues." (PMID 22428009, 2012). "The detailed CpG methylation level of primary leiomyoma (n = 8) and matched myometrial (n = 8) tissues verified the hypermethylated state of the KLF11 promoter in uterine leiomyoma compared with adjacent normal myometrium." (PMID 22428009, 2012). "Incubation of primary leiomyoma smooth muscle cells with a DNA methyltransferase inhibitor restored KLF11, DLEC1 and KRT19 mRNA levels." (PMID 22428009, 2012). "5-aza-dC treatment of primary cultured leiomyoma smooth muscle cells led to an increase in KLF11 mRNA by 1.4-fold, DLEC1 mRNA by 2-fold, and KRT19 mRNA by 2.4-fold suggesting that these three genes are epigenetically regulated in leiomyomas." (PMID 22428009, 2012). "To understand the in vivo relevance of how DNA methylation affects gene function, we analyzed protein levels of KLF11, DLEC1 and KRT19 in human leiomyoma and matched normal myometrial tissues using western blot." (PMID 22428009, 2012).
liver fibrosis (4 papers, 2013 to 2024). "Taken together, this data demonstrates that a downregulation in the level of KLF11 mRNA is associated with the cellular and molecular responses contributing to the genesis of liver fibrosis." (PMID 24069400, 2013). "Here, our results demonstrate that hepatocyte miR-30 greatly inhibits fibrotic TGF-β/Smad signaling by targeting KLF11 and consequently prevents liver fibrosis." (PMID 28592847, 2017). "Liver fibrosis is an ideal model system for investigating the pathobiological effects of altered KLF11 levels on cells of mesenchymal origin." (PMID 24069400, 2013). "Although KLF11 downregulates collagen I production and KLF11 deficiency enhances hepatic fibrosis, there have been no previous studies linking KLF11 signaling to fibrosis or inflammation in chronic renal injury, an issue that has been identified as an important area for future investigation." (PMID 35413089, 2022). "Thus, collectively, these studies assign a new function to KLF11 as a transcription factor that modulates mesenchymal cells function and participates in the pathobiological deregulation of these cells in an experimental model of liver fibrosis." (PMID 24069400, 2013).
lung carcinoma (4 papers, 2019 to 2024). "After hyperthermia combined with radiotherapy, KLF11 increased, which induced apoptosis and inhibited cell proliferation by increasing reactive oxygen species (ROS) level in lung cancer A549 cell lines." (PMID 38560274, 2024). "A study in 2019 found that the upregulation of KLF11 and NR4A3 is associated with the induction of apoptosis and ROS generation and is critical for slowing the progression of lung cancer." (PMID 37107299, 2023). "Small RNA interference with KLF11 gene transcription reduced radiothermotherapy efficacy; and the effect on lung cancer was confirmed in xenograft models, and might be a key factor in improving the efficacy of radiotherapy combined with chemotherapy." (PMID 38560274, 2024). "KLF11 is critical for increasing the sensitization of lung cancer to radiotherapy." (PMID 35387557, 2022). "A549 lung cancer cells exhibited increased levels of NR4A3 and KLF11 after combination therapy, which also induced apoptosis and inhibited cell proliferation by elevating intracellular ROS levels." (PMID 37107299, 2023). "We further delineate the EGR1 target genes in YYJD‐treated A549, including some apoptosis‐related genes such as KLF11,29, 30, 31 BCL2L1137, 38, 39, and DUSP6.40, 41 These observations suggest that the apoptosis of lung cancer cells induced by YYJD is possibly mediated by EGR1‐bound target genes." (PMID 31237749, 2019).
Obesity (4 papers, 2013 to 2024). Accumulation of substantial excess body fat. "Proportion of persons with obesity ranged from 0% (KCNJ11‐MODY) to 66.7% (KLF11‐MODY)." (PMID 39511990, 2024). "Interestingly, conventional KLF11 knockout protects against high-fat diet-induced obesity and increases metabolic rate in female mice." (PMID 39462409, 2024).
Anxiety (3 papers, 2017 to 2024). Intense feelings of nervousness, tension, or panic often arise in response to interpersonal stresses. "Given that MDD is highly comorbid not only with PD but also with other anxiety and mental disorders, the potential of KLF11 methylation status as a diagnostic marker to separate MDD diagnosis from other diagnoses should be explored in future studies." (PMID 32524199, 2020). "Murine studies find associations with Klf-9 and anxiety, and human studies link Klf-11 with chronic stress and depressive disorders." (PMID 29225348, 2017). "We found that CGRP modulates anxiety behavior by epigenetically regulating the HP1γ-KLF-11-MAOB pathway and depleting dopamine in the dorsal hippocampus." (PMID 38503899, 2024).
atherosclerosis (3 papers, 2022 to 2025). A disease characterized by the build-up of fatty material and calcium deposition in the arterial wall resulting in partial or complete occlusion of the arterial lumen. "Accordingly, endothelial KLF11 deficiency in the diabetic atherosclerosis model increased the binding activities of lipoprotein particles and growth factors and the expression of Notch1 and Snai1." (PMID 39462409, 2024). "Therefore, further research will be required to explore the potential for simultaneous or specific targeting of KLF11 by those known medications and natural bioactive compounds for treating atherosclerosis and associated disorders." (PMID 39462409, 2024). "In contrast, KLF11 gain‐of‐function attenuates atherosclerosis and enhances plaque stability via reducing glycolysis in KLF11−/− mice." (PMID 40397286, 2025). "KLF11 knockout abolished the inhibitory effect of wogonin on glycolysis, thereby exacerbating atherosclerosis and reducing the antiatherogenic effect of wogonin." (PMID 40397286, 2025). "Wogonin also promotes the KLF11 expression and KLF11 knockout exacerbated atherosclerosis and abolishes the inhibitory effect of wogonin on glycolysis and atherosclerosis." (PMID 40397286, 2025). "In contrast, KLF11 restoration in KLF11−/− mice attenuated atherosclerosis and enhanced plaque stability via reducing glycolysis." (PMID 40397286, 2025). "Of relevance, our scRNA-seq data uncovered potential metabolic effects of KLF11 on endothelial dysfunction and atherosclerosis." (PMID 39462409, 2024). "Given that females show more severe atherosclerosis under diabetic conditions, future research should include both male and female mice to better understand the sex-specific effects of KLF11 on EndMT." (PMID 39462409, 2024). "However, KLF11 knockout not only exacerbated atherosclerosis but also markedly abolished the antiatherogenic effect of wogonin by promoting glycolysis." (PMID 40397286, 2025). "Additionally, it will be necessary to dissect the different contributions of KLF11 to atherosclerosis in obesogenic vs. diabetogenic conditions by extending these transcriptomic studies to mice on western diet." (PMID 39462409, 2024). "KLF4 and BCLAF1 initiate SMC phenotypic switch in atherosclerosis by inducing SMC lipid transdifferentiation, whereas KLF11 has been shown to inhibit arterial thrombosis." (PMID 36188622, 2022). "Our study also identified specific atherosclerosis-related transcription factors KLF4, KLF11 and BCLAF1 upstream from FURIN, PCSK6 or PCSK7." (PMID 36188622, 2022). "The result showed that KLF11 restoration did not affect the lipid profile in the serum but mitigated the atherosclerosis and enhanced the plaque stability." (PMID 40397286, 2025). "Thus, whether and how KLF11 regulates GPX4 transcription and lipid peroxidation in ECs, probably affecting atherosclerosis under diabetic conditions, is a noteworthy possibility to explore." (PMID 39462409, 2024).
cardiac hypertrophy (3 papers, 2018 to 2024). "For example, KLF11 overexpression inhibits cardiac hypertrophy and fibrosis in mice subjected to the thoracic aortic constriction model of cardiac hypertrophy." (PMID 35413089, 2022). "KLF11 expression is reduced in hypertrophic mouse hearts and overexpression of cardiac KLF11 protected mice from cardiac hypertrophy induced with TAC." (PMID 29970016, 2018). "In addition to GATA, MEF2 and NFAT families, other transcription factors, such as UBF1 86, ATF3 87, T-Cdk9 88, XBP1 89, MITF 90, HSF1 91, C/EBP 92, KLF11 93 and KLF5/BTEB2 94 have been implicated in regulating cardiac hypertrophy." (PMID 39239522, 2024). "Of these only KLF4, KLF5, KLF10, KLF11 and KLF15 have been studied in cardiac hypertrophy." (PMID 29970016, 2018).